MMP9 (matrix metallopeptidase 9)
Diseases named in the same sentence as MMP9 in open-access papers (continued):
Sharing a sentence is not in itself a finding about the gene and the disease.
Hernia (6 papers, 2011 to 2025). "On the other hand, MMP-9 plasma levels were reduced in hernia patients compared to controls, and this result is in line with previous findings." (PMID 40806165, 2025). "In particular, MMP-9 levels in serum and/or tissues were found increased, unvaried, lower, or higher in tissues but lower in plasma of hernia patients compared to controls." (PMID 40806165, 2025). "MMP-2 was found to be abnormally high at both mRNA and protein levels in serum and fascial tissues of patients with ventral wall hernias; some studies showed that MMP-9 expression was increased in the hernia-positive group." (PMID 38591204, 2024). "In fact, increased levels of MMP, particularly MMP-9, have been found in patients with multiple venous diseases as well as hernias." (PMID 34439968, 2021). "The overexpression of PI16 inhibits MMP activity, and MMPs, including MMP1, MMP2, MMP9, and MMP13, are associated with abdominal hernia development." (PMID 34341761, 2021). "It has been discussed that MMP–9 inhibition modulates inflammatory reactions, resulting in faster neovascularization of connective tissues in an animal hernia model." (PMID 32230721, 2020). "However, MMP-9 did not emerge as an independent statistically significant predictor of hernia risk in our study." (PMID 40806165, 2025).
Hyperinsulinemia (6 papers, 2010 to 2023). An increased concentration of insulin in the blood. "In the hyperinsulinemia/euglycemic clamp model of EL, the cohort of genes examined included few downstream targets of IL-17A activation, but these studies identified both MMP9 and TNFα upregulation." (PMID 33301461, 2020). "In particular, hyperinsulinemia induces the production of matrix metalloproteinase-9 (MMP-9), which provokes plaque instability and rupture." (PMID 28372564, 2017). "In order to examine the effects of hyperinsulinemia on the metastasis of tumor cells from the primary site, we examined levels of c-Myc, MMP-9, IR, IGF-IR and VEGF in tumor tissue extracted from control and MKR+/+ mice." (PMID 22226054, 2012). "Under hyperglycemic conditions, hyperinsulinemia slightly upregulated CDH1 (FCHG, ins = 1.23) and COL1A1 expression (FCHG, ins = 0.75) compared to the respective untreated hyperglycemic controls, whereas MMP9 levels (FCHG, ins = 0.56) were downregulated." (PMID 37313172, 2023). "MMP9 expression (FCNG, 0.1+ins = 0.69; FCNG, 1.0+ins = 0.50, p = 0.089) was further decreased when 1.0 mmol/L metformin was administered under the influence of hyperinsulinemia in a normal glucose environment, indicating a supportive anti-metastatic effect." (PMID 37313172, 2023). "In contrast, CDH1 (FCHG, ins = 1.52), CDKN1A (FCHG, ins = 2.87), PTEN (FCHG, ins = 1.61) and MMP9 (FCHG, ins = 0.71) were slightly downregulated during hyperinsulinemia under the influence of a hyperglycemic environment, when compared to the respective untreated hyperglycemic control samples." (PMID 37313172, 2023).
Inguinal hernia (6 papers, 2009 to 2025). Protrusion of the contents of the abdominal cavity through the inguinal canal. "Serum IL-6, CRP, and MMP-9 levels in patients with inguinal hernia can affect the efficacy of modified preperitoneal Kugel repair and the prognosis of patients." (PMID 40292257, 2025). "Therefore, serum IL-6, CRP, and MMP-9 in patients with inguinal hernia before surgery will affect the surgical efficacy and prognosis of patients." (PMID 40292257, 2025). "In patients with inguinal hernia, serum IL-6, CRP, and MMP-9 increase first and then decrease after surgery, reaching the peak value around 24 or 48 h after surgery." (PMID 40292257, 2025). "For instance, MMPs (e.g., MMP‐1, MMP‐2, MMP‐9, MMP‐13) appear to be involved in inguinal hernia or recurrent inguinal hernia development." (PMID 31588690, 2019). "Preoperative MMP-9 levels in nasal secretions were found to show an inverse correlation with quality of healing after sinus surgery, while MMP-9 in wound fluid obtained at 24 hours after inguinal hernia surgery showed an inverse correlation with collagen deposition at 10 days." (PMID 19968600, 2009).
interstitial lung disease (6 papers, 2005 to 2024). A diverse group of lung diseases that affect the lung parenchyma. "MMP2 and MMP9 are the subgroup of MMPs that have been most extensively studied in interstitial lung diseases and their genes and proteins are upregulated in IPF." (PMID 25551570, 2014). "The contribution of interstitial lung disease to MMP-9 elevation may be obscured by the stronger effect of skin fibrosis." (PMID 15642145, 2005). "However, the presence of interstitial lung disease (ILD) did not affect MMP9 levels." (PMID 31440381, 2019).
ischemia reperfusion injury (6 papers, 2012 to 2023). Adverse functional, metabolic, or structural changes in ischemic tissues resulting from the restoration of blood flow to the tissue (reperfusion), including swelling; hemorrhage; necrosis; and damage from free radicals. "In addition, several studies demonstrated that doxycycline and minocycline inhibited MMP-2 and MMP-9 expression in animal models of ischemia reperfusion injury and thereby reduced the pathology." (PMID 28257106, 2017). "In addition, inhibiting the recruitment of PMN to the brain following ischemia-reperfusion injury prevents the increase in MMP-9." (PMID 22269349, 2012). "MMP-9 was found to be involved in ECM degradation with an effect in increasing matrix permeability-enhancing leukocyte infiltration and inflammation, leading to impaired liver function during ischemia reperfusion injury." (PMID 36837539, 2023).
metastatic prostate carcinoma (6 papers, 2012 to 2024). A carcinoma that arises from the prostate gland and has spread to other anatomic sites. "In metastatic prostate cancer, piperine regulated the Akt/mTOR/MMP-9 signaling pathway and reduced metastasis." (PMID 36678600, 2023). "A recent study found that L-theanine had the therapeutic potential for metastatic prostate cancer (PCa), since L-theanine inhibited the epithelial-mesenchymal transition process of PCa by downregulating matrix metallopeptidase 9 (MMP9), N-cadherin, Vimentin, and Snail, and upregulating E-cadherin." (PMID 35445053, 2022).
obstructive sleep apnea (6 papers, 2015 to 2025). "We aimed to investigate the associations between serum matrix metalloproteinase (MMP)-2 and MMP-9 levels and obstructive sleep apnea (OSA) severity with a focus on nocturnal hypoxemia." (PMID 40117070, 2025). "In fact, plasma MMP9 levels are elevated in patients with obstructive sleep apnea, and urinary MMP2 activity has been shown to increase in accordance with obstructive sleep apnea severity." (PMID 34512381, 2021).
Oral ulcer (6 papers, 2016 to 2025). Erosion of the mucous mebrane of the mouth with local excavation of the surface, resulting from the sloughing of inflammatory necrotic tissue. "Chrysin oral gel (1% and 2%) application for 7 days reduced MMP9 by 68% and 88%, respectively, compared to the oral ulcer group." (PMID 40809172, 2025). "Our results revealed that acetic acid application increased MMP9 buccal contents, inducing oral ulcers by 883% compared with the normal control group." (PMID 40809172, 2025). "The propolis-based treatment provoked greater expression of VEGF and smaller expression of MMP-9 in induced oral ulcers." (PMID 34667500, 2021). "KYQG exhibited the therapeutic effects on oral ulcers probably by inhibiting inflammation, regulating immunological response, and suppressing oxidative stress based on 47 key targets, such as MMP9, COX2, and TNF-α." (PMID 32811507, 2020). "KYQG markedly diminished inflammation and enhanced the healing of oral ulcers, as evidenced by reduced levels of inflammatory markers including COX-2, MMP-9, and TNF-α." (PMID 39907951, 2025). "To demonstrate the reliability of our method, we conducted the animal experiment on an oral ulcer model in rats and detected the serum levels of COX2, MMP9, and TNF-α." (PMID 32811507, 2020). "The results of the experimental verification indicated that KYQG significantly inhibited the serum levels of cyclooxygenase-2 (COX2), matrix metalloproteinase 9 (MMP9) and tumor necrosis factor-alpha (TNF-α) in rats with oral ulcer." (PMID 32811507, 2020). "In the component-key target network, PTGS2, referred to as cyclooxygenase 2 (COX2), MMP9, and TNF-α are the top three degree-ranked targets, which were considered as the important roles in oral ulcers treatment of KYQG." (PMID 32811507, 2020).
Peptic ulcer (6 papers, 2020 to 2024). The term peptic ulcer refers to acid peptic injury of the digestive tract, resulting in mucosal break reaching the submucosa. "In clinical samples, MMP-9 mRNA expression was found to be significantly upregulated in H. pylori-positive patients, with a notable association with CagA status and peptic ulcer disease (PUD)." (PMID 39712025, 2024). "The PPI network was constructed for the peptic ulcer genes, the constructed network to show the interactions between peptic ulcer targets proved that the following genes have the higher node degrees; AKT1, TNF, SRC, EGFR, ESR1, PTGS2, MMP9." (PMID 38728332, 2024).
peripheral nerve injury (6 papers, 2012 to 2026). Injury to a peripheral nerve. "After peripheral nerve injury, gelatinases B (MMP-9) and A (MMP-2) degrade the blood-nerve barrier, release the pro-inflammatory cytokines, control immune cell infiltration and cell survival along the injured neural axis." (PMID 22676642, 2012). "After peripheral nerve injury, the binding of FTO to MMP-9 mRNA decreased and the enrichment of m6A on MMP-9 mRNA increased." (PMID 35634463, 2022). "Previous reports suggested that gene knockout of MMP-9 or administration of inhibitors for general or specific inhibition of MMP-9 and MMP-2 reduced nociceptive pain behaviors induced by peripheral nerve injury." (PMID 28199982, 2017).
peritonitis (6 papers, 2015 to 2022). Inflammation of the peritoneum (tissue that lines the abdominal wall and covers most of the organs in the abdomen). "Zymosan-induced MMP-9 expression at the single-cell level during peritonitis is a quantitative indicator of the phase-specific contribution of mast cells, macrophages, and neutrophils." (PMID 27340562, 2016). "Here, we aim to investigate the role of MMP-9 for (mortality-) prognosis or indication for surgery in case of colic and also the possible use of MMP-9 for antibiotic stewardship during postoperative care and the management of complications like peritonitis or postoperative ileus." (PMID 33488296, 2021). "Therefore, we investigated whether the treatment with AGEs could attenuate the activation of MMP-9 in the peritonitis model." (PMID 35624109, 2022). "MMP-2 was associated with chemical peritoneal injury and showed increased levels in PD effluent in patients with peritoneal injury, while PD effluent levels of MMP-9 and TIMP-1 were higher in the onset of peritonitis." (PMID 31815017, 2019). "Mmp9, Rgs2 and Zfp36l2 were downregulated in both IL-1β-induced conditions, while Lyz2 and Lst1 were downregulated in IL-1β-induced pneumonitis but not peritonitis." (PMID 34001893, 2021).
pressure ulcers (6 papers, 2008 to 2025). "Patients who have a Rs1056629 polymorphism in the MMP9 gene are more likely to develop pressure ulcers due to impaired miR-491-5p binding, which typically inhibits MMP9 activity." (PMID 33374656, 2020). "Pressure ulcers have increased levels of MMP9 and decreased levels of tissue inhibitor metalloproteinase-1 (TIMP-1), and wounds with higher MMP9 and lower TIMP-1 activity heal slower than those with opposite relative levels." (PMID 33374656, 2020). "Critical pathways involved in miRNA regulation of pressure ulcer pathophysiology include PI3K/AKT, p38-MAPK, NFκB, and MMP9." (PMID 33374656, 2020). "It has been reported that matrix metalloproteinase-9 (MMP-9) protein levels are elevated in human non-healing pressure ulcers." (PMID 38132176, 2023).
proliferative diabetic retinopathy (6 papers, 2008 to 2026). Advanced retinopathy due to diabetes mellitus characterized by the formation of new vessels in the retina. "The objective of the present study was to test for a possible association of five single nucleotide polymorphisms (SNPs) in the MMP-2 gene and two polymorphisms in the MMP-9 gene with proliferative diabetic retinopathy (PDR) and to determine their plasma levels." (PMID 18552985, 2008). "In proliferative diabetic retinopathy, the elevated levels of MMP-2 and MMP-9 were shown to cause ECM remodeling further leading to net collagen IV degradation and vitreous liquefaction." (PMID 29312345, 2017). "These authors concluded that correlations between VEGF and MMP-9 and TIMP-4 were found more in the eye tissue for patients with proliferative diabetic retinopathy, which characterizes with increased neo-angiogenesis." (PMID 35655767, 2022). "Significant positive correlations between TIMP-1, MMP-9, and VEGF vitreous fluid levels in proliferative diabetic retinopathy were clinically confirmed." (PMID 33218057, 2020). "The published literature and our previously published data demonstrated elevated levels of MMP-9 in the epiretinal membranes and vitreous fluid from patients with proliferative diabetic retinopathy (PDR) and increased MMP-9 expression in the retinas of diabetic rodents." (PMID 23671886, 2013).
prostate (6 papers, 2014 to 2023). "However, a tendency toward elevation of MMP-9 levels was observed in the CR kidney transplant patients." (PMID 24741575, 2014).
psychosis (6 papers, 2017 to 2025). "Our findings show an association between MMP-9 activity and hippocampal microstructural alterations in psychosis and an association between MMP-9 activity and cognitive performance." (PMID 38431757, 2024). "The present study aims to build on these findings by applying Free-Water Imaging to study the association between peripheral MMP-9 activity, hippocampal microstructure, and cognition in 39 individuals with early phase psychosis and 44 healthy individuals." (PMID 38431757, 2024). "While analyses examining the association between MMP-9 gene polymorphisms and psychosis risk are inconclusive, several clinical studies reported peripheral MMP-9 upregulation in individuals with psychosis." (PMID 38431757, 2024). "We demonstrated that peripheral MMP-9 upregulation was associated with hippocampal volume loss in individuals with psychosis." (PMID 38431757, 2024). "The present study is the first to report an association between peripheral MMP-9 activity and extracellular hippocampal FW in early phase psychosis." (PMID 38431757, 2024). "Overall, we revealed that psychotic disorders are associated with increased CSF-to-serum albumin ratio, and increased blood S100B, MMP-9, and zonulin." (PMID 37692299, 2023). "We hypothesize that peripheral MMP-9 activity will be increased in individuals with early phase psychosis and that this increase will be associated with microstructural brain abnormalities." (PMID 38431757, 2024). "Increasing evidence points toward the role of the extracellular matrix, specifically matrix metalloproteinase 9 (MMP-9), in the pathophysiology of psychosis." (PMID 38431757, 2024). "In line with previous studies, individuals with early phase psychosis presented with higher MMP-9 activity than healthy individuals." (PMID 38431757, 2024). "Here, we aim to characterize the relationship between plasma MMP-9 activity, hippocampal microstructure, and cognition in healthy individuals and individuals with early phase psychosis." (PMID 38431757, 2024). "MMP-9 activity correlated positively with hippocampal FW levels (all participants and individuals with early phase psychosis) and negatively with hippocampal volumes (all participants and healthy individuals)." (PMID 38431757, 2024). "While no previous studies directly examined the relationship between MMP-9, brain structure, and cognitive performance in psychosis, several studies in other conditions support our findings." (PMID 38431757, 2024). "Further, more extensive longitudinal studies should examine the therapeutic potential of MMP-9 modulators in psychosis." (PMID 38431757, 2024). "Individuals with early phase psychosis demonstrated higher peripheral MMP-9 activity, higher hippocampal FW, and lower hippocampal volumes than healthy individuals." (PMID 38431757, 2024). "Individuals with early phase psychosis demonstrated higher MMP-9 activity (p < 0.0002), higher left (p < 0.05) and right (p < 0.05) hippocampal FW levels, and lower left (p < 0.05) and right (p < 0.05) hippocampal volume than healthy individuals." (PMID 38431757, 2024). "Larger, transdiagnostic studies are needed to address MMP-9 sensitivity and specificity to psychosis in order to examine if MMP-9 can be used as a peripheral biomarker to identify vulnerable individuals or to monitor treatment response." (PMID 38431757, 2024). "Patients with psychosis were found to have higher blood matrix metalloproteinase-9 (MMP-9; SMD, 0.66; 95% CI, 0.46–0.86; p < 0.001)." (PMID 37692299, 2023). "Studies from different fields examined the role of MMP-9 in psychosis." (PMID 38431757, 2024). "Similar to the MMP-9 upregulation, the association with cognition is also not specific to psychosis, suggesting a physiological link between MMP-9 activity and cognition." (PMID 38431757, 2024).
psychosis (continued). "The associations between MMP-9 activity and the right hippocampal volume in healthy individuals, and left and right hippocampal volumes in individuals with psychosis were not quite significant after Bonferroni-correction." (PMID 38431757, 2024). "Another study indicated that MMP-9 might be a good marker to discriminate individuals with psychosis from healthy individuals, and a recent one examined the potential of modifiable factors such as smoking and medication on this upregulation." (PMID 38431757, 2024). "Furthermore, we focused our analyses on the hippocampus, given its role in psychosis and the previously reported link between MMP-9 levels and the hippocampus." (PMID 38431757, 2024). "The elevation of blood MMP-9 in psychosis in our analyses may in part reflect ongoing inflammation that disrupts endothelial structure." (PMID 37692299, 2023). "Finally, we observed greater sensitivity to psychosis‐related locomotor hyperactivity in Mmp‐9 heterozygous mice." (PMID 28623238, 2017). "The suppression of MMP-9 expression and activation by haloperidol in vitro and in vivo may explain its crucial role as a bystander in antineuroinflammatory actions for the treatment of psychotic disorders." (PMID 29849502, 2018). "Postmortem studies in humans demonstrated an upregulation of MMP-9 and increased MMP-9 in the cerebrospinal fluid of individuals with psychosis." (PMID 38431757, 2024). "Indeed, some preliminary evidence indicated that MMP-9 inhibition might benefit psychosis outcomes." (PMID 38431757, 2024). "However, further multimodal studies are needed to validate this assumption, examine the association between MMP-9 and other peripheral and central markers of inflammation, and truly understand the role of MMP-9 in the crosstalk between peripheral and central inflammation in psychosis." (PMID 38431757, 2024). "MMP-9 levels were not elevated in psychiatric control conditions, and the study also did not observe a difference between individuals with first-episode psychosis versus non-first-episode psychosis." (PMID 38431757, 2024). "Of note, it does not seem that MMP-9 activation is specific for psychosis." (PMID 38431757, 2024).